OFD1 (OFD1 centriole and centriolar satellite protein)
Diseases named in the same sentence as OFD1 in open-access papers (continued):
Sharing a sentence is not in itself a finding about the gene and the disease.
vitiligo (1 paper, 2023). Generalized well circumscribed patches of leukoderma that are generally distributed over symmetric body locations and is due to autoimmune destruction of melanocytes. "Our study also revealed a downregulation of oral–facial digital syndrome type 1 (OFD1) in the affected skin of vitiligo patients." (PMID 38139355, 2023). "The findings presented in this study strongly support the downregulation of OFD1 in the lesional epidermis of vitiligo patients." (PMID 38139355, 2023). "In this study, we investigated the role of OFD1 in vitiligo, particularly focusing on melanocyte apoptosis." (PMID 38139355, 2023). "Downregulation of paxillin was also detected in the lesional epidermis of vitiligo patients with OFD1 downregulation." (PMID 38139355, 2023). "In our study, we observed reduced levels of paxillin, FAK, and integrin β1 in melanocytes following OFD1 knockdown and the lesional epidermis of vitiligo patients." (PMID 38139355, 2023). "OFD1 knockdown, which was achieved using CRISPR technology to minimize off-target effects of siRNA, resulting in increased apoptosis in both melanocytes and keratinocytes, suggesting that OFD1 downregulation may play a significant role in vitiligo." (PMID 38139355, 2023). "In summary, our findings suggest that OFD1 downregulation induces melanocyte apoptosis and vitiligo, independent of impaired ciliogenesis, by reducing melanocyte adhesion to the ECM through paxillin." (PMID 38139355, 2023).
X-linked dominant disease (1 paper, 2018). X-linked dominant form of disease. "The majority of the OFD1 mutations were associated with OFD1 syndrome, which is a male-lethal X-linked dominant disease characterized by malformations of the face, oral cavity, and digits." (PMID 30581852, 2018).
cancer (14 papers, 2020 to 2025). A tumor composed of atypical neoplastic, often pleomorphic cells that invade other tissues. "Consistent with the important role of OFD1 to ensure the fidelity of mitosis, increased OFD1 expression is found to be associated with malignant transformation in multiple cancer types." (PMID 36973243, 2023). "Due to OFD1 being an X-linked gene, male cancer cells can be rendered cilia-less by a single damaging point mutation in OFD1, potentially increasing their proliferative capacity." (PMID 37852252, 2023). "Upon DOX addition, the proliferation of most cancer cell lines was inhibited, correlating with the loss of OFD1 expression." (PMID 36973243, 2023). "Oncogene-transformed cells are able to bypass cell cycle arrest caused by OFD1 loss, but whether this property leads to the growth advantage of cancer cells is unknown." (PMID 36973243, 2023). "Most encouragingly, loss of OFD1 mainly kills cancer cells but only causes reversible cell cycle arrest in normal cells, suggesting that fewer side effects may occur upon the treatment." (PMID 36973243, 2023). "From the gene-interaction network analysis, we found that the genes with survival-associated AS events including HNRNPA1, RPS5, DDX55, and OFD1 were hub nodes of the network which might play vital roles in cancer progress." (PMID 32595697, 2020). "Given the unique and robust regulation of BRCA1 expression by OFD1, targeting OFD1 offers a promising strategy for extending the use of PARP inhibitor therapy to BRCA1 wide-type cancers." (PMID 40764600, 2025). "In this study, we reveal the unanticipated role of OFD1 inhibition in inducing the BRCAness phenotype in cancer." (PMID 40764600, 2025). "OFD1 is highly expressed in various cancer types, and knockdown of OFD1 suppresses the growth of multiple cancer cell lines in mouse xenograft models." (PMID 40764600, 2025). "To test if OFD1 expression sustains cancer cell proliferation, we generated multiple DOX-dependent inducible OFD1 knockdown cancer cell lines." (PMID 36973243, 2023). "Taken together, OFD1-depleted, oncogenic-transformed cells bypass cell cycle arrest but fail to form functional actomyosin ring and undergo irreversible mitotic catastrophe, which leads to a preferential killing effect when OFD1 is inhibited in cancer cells." (PMID 36973243, 2023). "Since we observed that OFD1 depletion kills cancer cells but arrests normal cells in quiescence, we anticipated that the growth inhibition of OFD1 depletion should be reversible in normal cells but not in cancer cells." (PMID 36973243, 2023). "The DOX diet was started on day 24 post cancer cell implantation when the xenografts from cells with inducible OFD1 shRNA grew to an average volume of 200–300 mm3." (PMID 36973243, 2023). "Targeting OFD1 for destruction suppresses tumor cell growth in cultures and mouse xenograft models, indicating that OFD1 is an attractive target for cancer therapy." (PMID 36973243, 2023). "Strikingly, temporal targeting of OFD1 killed cancer cells irreversibly but normal cells grew back upon restoration of OFD1 expression." (PMID 36973243, 2023). "Although lymphocytes are not ciliated, our results highlight the vulnerability of the OFD1 locus and hence the ciliogenesis pathway in other cell types in cancer." (PMID 37852252, 2023). "One important element, OFD1, is employed to prevent primary cilia in human cancer cells from growing." (PMID 36467412, 2022). "However, conditional knockout of Ofd1 in adult mouse pancreas had minimal effect on lifespan, suggesting a potential therapeutic window for targeting OFD1 in cancer therapy." (PMID 40764600, 2025). "Considering the suppressive role of OFD1 in cilia formation, there is a possibility that OFD1 may function to inhibit ciliogenesis in tumors and promote cancer cell proliferation." (PMID 36973243, 2023). "Taken together, OFD1 is a promising therapeutic target for cancer treatment." (PMID 36973243, 2023).
cancer (continued). "Targeting OFD1 and/or its mediated actin filament branching surveillance system may provide a direction for cancer therapy." (PMID 36973243, 2023). "OFD1 depletion by DOX largely attenuated cancer xenograft development in all three models." (PMID 36973243, 2023). "We analyzed OFD1 expression in cancers from the TCGA database." (PMID 36973243, 2023). "Thus, targeting OFD1-mediated actin filament branching surveillance system provides a direction for cancer therapy." (PMID 36973243, 2023). "Inhibition of OFD1 leads to suppression of multiple cancer cell growth in mouse xenograft models." (PMID 36973243, 2023). "Given the crucial role of OFD1 in cell cycle progression, we speculate that cancer cells increase OFD1 levels to maintain sustainable division." (PMID 36973243, 2023). "In addition, we also found the high expression of OFD1 in CMPTs by immunohistochemistry, which is an important inhibitor of primary cilia in cancer cells." (PMID 33133167, 2020). "Thus, OFD1 depletion mimics BRCA1 deficiency and may serve as a potential therapeutic strategy to sensitize HRR-proficient cancers to PARP inhibition." (PMID 40764600, 2025). "Notably, our recent studies have indicated a potential role of OFD1 in cancer." (PMID 40764600, 2025). "In conclusion, our study demonstrates that OFD1 inhibition triggers the BRCAness phenotype, with significant implications for sensitizing BRCA1/2 proficient cancers to PARPi." (PMID 40764600, 2025). "Second, the proposed approach also enables identification and exploration of driver genes; our analyses implicate DMD, RSK4, OFD1, WDR44, and AFF2 as potential cancer drivers." (PMID 35753349, 2022). "Of note, USP9X (log2FC/FDR = −0.31/1.7e-06), a previously reported cancer driver, TXLNG (−0.54/3.3e-17), OFD1, MED14, and CDK16 are known to evade X-inactivation and were over-expressed in females’ GC." (PMID 32849808, 2020). "To verify this hypothesis, we performed a DOX washout experiment to temporally knockdown OFD1 in normal cells, RPE1, as well as multiple cancer cell lines, including ACHN, MDA-MB-231, and PANC-1." (PMID 36973243, 2023). "On the contrary, partial depletion of OFD1 in non-transformed RPE1 and MEF cells as well as MCF7 cancer cells using RNAi technique to remove the centriolar satellite pool while maintaining the centriole pool of OFD1 promotes primary cilia formation." (PMID 33304902, 2020). "OFD1 sustains cancer cell growth by promoting actin filament branching, and insufficient actin branching due to a lack of OFD1 decreases the growth advantage of cancer cells and results in irreversible killing." (PMID 36973243, 2023). "Although OFD1 is not directly involved in DNA damage repair, it regulates BRCA1 transcription in a stress-inducible manner, making it a promising target for cancer therapy." (PMID 40764600, 2025).
tumor (7 papers, 2016 to 2025). "Across all tumor types, the combination of doxycycline and olaparib showed the most pronounced tumor regression compared to that of the other groups, demonstrating a strong synergistic effect of OFD1 inhibition and PARPi on BRCA-associated tumors." (PMID 40764600, 2025). "Seven potential tumor antigens, [SREBF1, LUC7L3, LAMA5, PCGF3, HNRNPH1, KLC4, and OFD1], which were associated with nonsense-mediated mRNA decay factor expression, overall survival, and infiltration of APCs and would thus induce a potent anti-tumor T-cell response." (PMID 39399167, 2024). "We evaluated OFD1 expression in human tumor tissues and peri-cancerous tissues surgically resected from 90 PDAC patients using IHC with validated OFD1 and BRCA1 antibodies." (PMID 40764600, 2025). "Next, we treated MIA PaCa-2 orthotopic tumor-bearing mice with vehicle, shOFD1, olaparib, and the combination of OFD1 knockdown and olaparib over an extended treatment period." (PMID 40764600, 2025). "While the vehicle and olaparib treatment groups exhibited significant tumor burden, the OFD1 knockdown group showed a marked reduction in tumor burden." (PMID 40764600, 2025). "SW1990-shOFD1 tumors treated with olaparib showed a significant reduction in tumor growth rate, tumor mass, and tumor proliferation compared to tumors with either OFD1 knockdown or olaparib treatment alone." (PMID 40764600, 2025). "Our findings demonstrate that targeting OFD1 in combination with olaparib leads to a synergistic anti-tumor effect in various PDAC models, including xenografts, orthotopic models, PDX and spontaneous KPC models." (PMID 40764600, 2025). "Xenograft tumors derived from KPC1199 cells with Ofd1 knockout treated with olaparib showed a marked reduction in tumor growth and volume." (PMID 40764600, 2025). "Correlating tumor OFD1 expression with survival data showed that patients with higher OFD1 expression in their tumors had poorer median survival." (PMID 40764600, 2025). "Depletion of OFD1 by RNA interference largely attenuates tumor growth in culture cells and mouse xenograft models." (PMID 36973243, 2023). "Notably, mice treated with the combination of OFD1 knockdown and olaparib had tumor burden reduced to nearly undetectable levels." (PMID 40764600, 2025). "In addition, analysis of the relative pancreas mass at the endpoint (day 78) revealed significant tumor regression in the combination of OFD1 knockdown and olaparib group." (PMID 40764600, 2025). "Mutations in OFD1 lead to cilia loss, resulting in slow-growing, GLI2-dependent resistant tumours." (PMID 39568072, 2024). "The doxycycline-induced knockdown of OFD1 and downregulation of BRCA1 in tumor tissues were validated by western blot analysis." (PMID 40764600, 2025). "In our study, we identified a series of potential tumor antigens, including SREBF1, LUC7L3, LAMA5, PCGF3, HNRNPH1, KLC4, and OFD1, by systematically analyzing alternative splicing and mutation of genes in patients with HNSCC." (PMID 36467412, 2022).
genetic disease (3 papers, 2022 to 2025). "The extensive spectrum of clinical manifestations observed in OFD1‐mutated patients represents a paradigmatic example of the complexity of genetic diseases." (PMID 35112477, 2022). "Mutations in OFD1 can lead to OFD1 syndrome, which is a rare genetic disorder." (PMID 38410514, 2024).
OFD1 also shares sentences with these, for which no sentence is quoted: Simpson-Golabi-Behmel syndrome type 2 (6 papers); Intellectual disability (3); retinal disease (3); retinitis pigmentosa 23 (3); Adult onset (2); Bardet-Biedl syndrome (2); Leber congenital amaurosis (2); polydactyly (2); prostate carcinoma (2); Retinal dystrophy (2); autosomal dominant polycystic kidney disease (1); autosomal recessive polycystic kidney disease (1); blood cancer (1); bone disorder (1); cleft palate (1); colon adenocarcinoma (1); colon cancer (1); colorectal cancer (1); cone dystrophy (1); cone-rod dystrophy (1); congenital heart malformation (1); cranioectodermal dysplasia (1); cryptosporidiosis (1); developmental delay (1); Encephalocele (1); Hydrocephalus (1); hypogonadotropic hypogonadism (1); ischemic stroke (1); Kabuki syndrome (1); kidney disease (1).
A further 26 diseases each share a sentence with OFD1 in 1 paper.